ENSG00000169164 (X antigen family, member 3 (XAGE3) pseudogene)
Synonyms: XAGE-4
Gene: Transcribed unprocessed pseudogene on chromosome X (55,654,709 to 55,657,014, reverse strand). Ensembl gene ENSG00000169164.
Diseases named in the same sentence as ENSG00000169164 in open-access papers:
ENSG00000169164 is named in the same sentence as 1 disease in open-access papers, as found by Europe PMC text mining. Sharing a sentence is not in itself a finding about the gene and the disease.
ENSG00000169164 shares sentences with these, for which no sentence is quoted: triple-negative breast carcinoma (1 paper).